IKBKG (inhibitor of nuclear factor kappa B kinase regulatory subunit gamma)
Description:
Regulatory subunit of the IKK core complex which phosphorylates inhibitors of NF-kappa-B thus leading to the dissociation of the inhibitor/NF-kappa-B complex and ultimately the degradation of the inhibitor. Its binding to scaffolding polyubiquitin plays a key role in IKK activation by multiple signaling receptor pathways. Can recognize and bind both 'Lys-63'-linked and linear polyubiquitin upon cell stimulation, with a much higher affinity for linear polyubiquitin. Could be implicated in NF-kappa-B-mediated protection from cytokine toxicity. Essential for viral activation of IRF3. Involved in TLR3- and IFIH1-mediated antiviral innate response; this function requires 'Lys-27'-linked polyubiquitination. (Microbial infection) Also considered to be a mediator for HTLV-1 Tax oncoprotein activation of NF-kappa-B.
Synonyms: NEMO; IKKAP1; IKK-gamma; IKKG; FIP3; Fip3p; FIP-3; AMCBX1; EDAID1; IMD33; IP; IP1; IP2; IPD2; SAIDX; ZC2HC9
Tractability: Small molecule: a structure with a bound ligand is known; a high-quality ligand is known; it belongs to a druggable protein family. PROTAC: UniProt records ubiquitination sites on it; ubiquitination databases record sites on it; its protein half-life has been measured; a small molecule that binds it is known.
Target class: Kinase; Protein kinase regulatory subunit; Enzyme
Gene: Protein-coding gene on chromosome X (154,541,179 to 154,565,047, forward strand). Ensembl gene ENSG00000269335.
Subcellular location: Cytoplasm; Nucleus
Subcellular location (Human Protein Atlas): Cytosol
Pathways (Reactome):
Immune System: Activation of NF-kappaB in B cells; CLEC7A (Dectin-1) signaling; Downstream TCR signaling; ER-Phagosome pathway; FCERI mediated NF-kB activation; IKK complex recruitment mediated by RIP1; IRAK1 recruits IKK complex; IRAK1 recruits IKK complex upon TLR7/8 or 9 stimulation; Interleukin-1 signaling; JNK (c-Jun kinases) phosphorylation and activation mediated by activated human TAK1; MAP3K8 (TPL2)-dependent MAPK1/3 activation; Modulation of host responses by IFN-stimulated genes; NF-kB activation through FADD/RIP-1 pathway mediated by caspase-8 and -10; NOD1/2 Signaling Pathway; PKR-mediated signaling; RIP-mediated NFkB activation via ZBP1; Regulation of NF-kappa B signaling; SLC15A4:TASL-dependent IRF5 activation; TAK1-dependent IKK and NF-kappa-B activation; TICAM1, RIP1-mediated IKK complex recruitment; TRAF6 mediated NF-kB activation; activated TAK1 mediates p38 MAPK activation
Disease: IKBKB deficiency causes SCID; IKBKG deficiency causes anhidrotic ectodermal dysplasia with immunodeficiency (EDA-ID) (via TLR); IkBA variant leads to EDA-ID; SARS-CoV-2 activates/modulates innate and adaptive immune responses
Metabolism of proteins: Ovarian tumor domain proteases; SUMOylation of immune response proteins; Ub-specific processing proteases
Signal Transduction: Regulation of TNFR1 signaling; TNFR1-induced NF-kappa-B signaling pathway
Cellular responses to stimuli: Turbulent (oscillatory, disturbed) flow shear stress activates signaling by PIEZO1 and integrins in endothelial cells
Gene Ontology:
Molecular function: identical protein binding; K63-linked polyubiquitin modification-dependent protein binding; linear polyubiquitin binding; polyubiquitin modification-dependent protein binding; protein binding; protein domain specific binding; protein heterodimerization activity; protein homodimerization activity; signaling adaptor activity; transferrin receptor binding; ubiquitin protein ligase binding
Biological process: canonical NF-kappaB signal transduction; defense response to bacterium; DNA damage response; establishment of vesicle localization; positive regulation of canonical NF-kappaB signal transduction; positive regulation of T cell receptor signaling pathway; positive regulation of transcription by RNA polymerase II; protein-containing complex assembly; anoikis; apoptotic process; immune response; inflammatory response; innate immune response; positive regulation of macroautophagy; positive regulation of ubiquitin-dependent protein catabolic process; response to virus; T cell receptor signaling pathway; negative regulation of endoplasmic reticulum stress-induced intrinsic apoptotic signaling pathway; positive regulation of gene expression
Cellular component: cytoplasm; cytosol; IkappaB kinase complex; mitotic spindle; nucleus; protein-containing complex; spindle pole; ubiquitin ligase complex; nucleoplasm
Gene-disease validity (ClinGen):
ClinGen rates the evidence that IKBKG causes each of these diseases.
IKBKG-related immunodeficiency with or without ectodermal dysplasia (X-linked): Definitive. Any recessive immunodeficiency (ID), with or without ectodermal dysplasia (EDA), in which the cause of the disease is mutation in the IKBKG gene.
incontinentia pigmenti (X-linked): Definitive. Incontinentia pigmenti (IP) is a rare X-linked dominant multi-systemic ectodermal dysplasia usually lethal in males and presenting neonatally in females with a bullous rash along Blashko's lines (BL) followed by verrucous plaques evolving over time to hyperpigmented swirling patterns.
Homologues: Orthologues: chimpanzee IKBKG (99% identical), macaque IKBKG (99% identical), dog IKBKG (90% identical), pig IKBKG (88% identical), rat Ikbkg (87% identical), guinea pig IKBKG (87% identical), mouse Ikbkg (87% identical), rabbit IKBKG (84% identical), tropical clawed frog ikbkg (49% identical), zebrafish ikbkg (45% identical). Paralogues in human: OPTN (29% identical).
Diseases named in the same sentence as IKBKG in open-access papers:
IKBKG is named in the same sentence as 256 diseases in open-access papers, as found by Europe PMC text mining. Sharing a sentence is not in itself a finding about the gene and the disease. The quoted sentences say what the papers report.
incontinentia pigmenti (72 papers, 2009 to 2025). "Incontinentia Pigmenti is a rare neuroectodermal disorder that is observed in female carriers with heterozygous pathogenic variants in the IKBKG gene." (PMID 39860371, 2025). "Incontinentia pigmenti (IP) is caused by loss-of-function variants in IKBKG, with molecular genetic diagnosis complicated by a pseudogene." (PMID 39975911, 2025). "Incontinentia pigmenti (IP) is a rare neuroectodermal dysplasia caused by a defect in the IKBKG gene." (PMID 38773385, 2024). "Incontinentia pigmenti (IP), also known as Bloch-Sulzberger syndrome, is a rare hereditary genodermatosis related to a mutation in the IKBKG gene." (PMID 39086952, 2024). "Molecular genetic testing was conducted to identify IKBKG mutations, and the case was finally diagnosed with incontinentia pigmenti complicated by central nervous system anomalies." (PMID 39882206, 2024). "The causative gene for incontinentia pigmenti, IKBKG/NEMO, has a complex structure and includes pseudogenes." (PMID 39271608, 2024). "Incontinentia pigmenti (IP), an X-chromosome dominant genodermatosis caused by mutations in the IKBKG/NEMO gene, is a rare disease affecting the skin, teeth, eyes, and central nervous system." (PMID 38173938, 2023). "We have identified a novel pathogenic mutation in the IKBKG gene encoding NEMO in a patient suffering from Incontinentia pigmenti (IP)." (PMID 36720498, 2023). "Incontinentia pigmenti (IP) is a rare neuroectodermal dysplasia caused by mutations in the IKBKG gene." (PMID 37250637, 2023). "Cleavage of NEMO by Mpro mimics the genetic disease incontinentia pigmenti that is caused by inactivating mutations in the NEMO (IKBKG) gene." (PMID 34675436, 2021). "We identified a novel IKBKG variant in a 7-month-old boy with pneumococcal rib osteomyelitis and later found that his mother has incontinentia pigmenti." (PMID 35003103, 2021). "Incontinentia pigmenti (IP) is a rare X‐linked disorder affecting the skin and other ectodermal tissues that is caused by mutation of the IKBKG/NEMO gene." (PMID 33085210, 2020). "Mutation in IKBKG gene is closely related to CNS anomalies in incontinentia pigmenti patients and Alzheimer’s disease." (PMID 28792504, 2017). "This can be compared to the IKBKG gene associated with incontinentia pigmenti." (PMID 40083426, 2025). "It was also found that mutations in the IKBKG gene, also known as nuclear factor-kappa B (NF-kB) essential modulator (NEMO), are the most frequent single cause of incontinentia pigmenti (IP) in women and anhydrotic ectodermal dysplasia with immunodeficiency (EDA-ID) in men." (PMID 39768951, 2024). "A similar situation exists for other X-linked genes such as IKBKG (loss-of-function variants cause incontinentia pigmenti (MIM# 308300) in females; variants with less severe consequences cause hypohidrotic ectodermal dysplasia and immunodeficiency (MIM# 300291) in males)." (PMID 37704779, 2023). "IKBKG mutations are related to two clinically distinct hereditary genetic diseases, incontinentia pigmenti (IP, OMIM #308300) and anhidrotic ectodermal dysplasia with immunodeficiency (EDA-ID, OMIM #300291), depending on genetic status and their inhibitory effects on NF-κB activation." (PMID 35887342, 2022). "On the other hand, mutated IKBKG, which is causative of Incontinentia pigmenti (OMIM #308300), leads to short stature, abnormal eye development, hypodontia, and may also affect the central nervous system." (PMID 36553593, 2022). "An IKBKG variant is also associated with incontinentia pigmenti (IP) in females." (PMID 35003103, 2021). "Moreover, there are additional genes with fully/variable escape patterns or female bias profile related to essential biological functions or clinical conditions, such as IKBKG, associated to Incontinentia Pigmenti." (PMID 32194616, 2020).
incontinentia pigmenti (continued). "For example, skewed inactivation has been reported in rearrangement and truncation mutations that result in a loss of function in the NEMO (IKBKG) gene, which is associated with incontinentia pigmenti, hypohidrotic ectodermal dysplasia, and other types of immunodeficiencies." (PMID 23634718, 2013). "However, heterozygous amorphic IKBKG variants could be responsible for Incontinentia Pigmenti (IP) in female carriers." (PMID 39860371, 2025). "Incontinentia pigmenti (IP) is an X-linked dominant multisystemic disorder caused by pathogenic variants in the IKBKG gene." (PMID 39623400, 2024). "Incontinentia pigmenti (IP) is an X-liked dominant genodermatosis caused by mutations of the IKBKG/NEMO gene." (PMID 35768795, 2022). "Examples of allelic disorders are the different variants in the IKBKG gene, which can cause incontinentia pigmenti (IP) if dysfunction is severe, ectodermal dysplasia if dysfunction is moderate, and immunodeficiency 33 if it is mild." (PMID 32284538, 2020). "Females with a single copy defect in the X-linked IKBKG gene (coding for NEMO) develop Incontinentia Pigmenti (IP), which is characterized by skin inflammation during the early stages of life." (PMID 31457011, 2019). "Most known variants including the presumed complete loss-of-function variants in the human IKBKG gene lead to an ED with characteristic clinical features termed incontinentia pigmenti (IP, OMIM #308300)." (PMID 24324710, 2013). "IKBKG activates NF-κB, and its highest level of expression is in the CNS, which suggests why seizures are common in patients with incontinentia pigmenti." (PMID 40083426, 2025). "Incontinentia pigmenti (IP, also called Bloch-Sulzberger syndrome, OMIM #308,300) is an X-linked, neurocutaneous disorder caused by a mutation in the IKK-gamma gene (IKBKG), also called NEMO, on chromosome Xq28." (PMID 37847489, 2024). "Autosomal dominant mutations in the IKBKG gene (also known as NEMO), are responsible for the cutaneous lesions of incontinentia pigmenti." (PMID 38510838, 2024). "The streaky skin pigmentation in F1, F3 and F5 led to incontinentia pigmenti being considered and IKBKG gene testing being arranged." (PMID 37704779, 2023). "Amorphic or hypomorphic mutations in the NEMO-encoding IKBKG gene located on the X-chromosome are associated with Incontinentia pigmenti (IP), a condition that is usually lethal in male fetuses and thus almost exclusively occurs in female patients with mosaic X-chromosome inactivation." (PMID 38114471, 2023). "Loss-of-function (amorphic) mutations in IKBKG result in incontinentia pigmenti (IP)." (PMID 36733767, 2022). "Mutations in NEMO, an essential modulator of NF-κB encoded by IKBKG, are associated with incontinentia pigmenti and X-linked ectodermal dysplasia with immunodeficiency." (PMID 34163478, 2021). "Mutations in IKBKG, the gene that encodes NEMO, are associated with both incontinentia pigmenti and X-linked recessive ectodermal dysplasia with immunodeficiency." (PMID 32671059, 2020). "Incontinentia Pigmenti (IP, OMIM#308300), which is caused by mutations of the IKBKG/NEMO gene, is a rare X-linked genomic disorder (1∶10000/20∶000) that affects the neuroectodermal tissues." (PMID 24489960, 2014). "Incontinentia pigmenti (IP) (Bloch-Sulzberger-syndrome, OMIM #308300) is a rare hereditary multisystemic neuroectodermal disorder caused by pathogenic variants in the IKBKG gene (formerly known as NEMO (nuclear factor-kappa B (NF-kB) essential modulator)) on X chromosome." (PMID 40677924, 2025). "However, some genes have complex structures that are difficult to analyze, including the OPN1LW/OPN1MW gene cluster in blue cone monochromacy and the IKBKG/NEMO genes in incontinentia pigmenti." (PMID 39271608, 2024).
incontinentia pigmenti (continued). "Genetic hypomorphic defects in X chromosomal IKBKG coding for the NF-κB essential modulator (NEMO) lead to ectodermal dysplasia and immunodeficiency in males and the skin disorder incontinentia pigmenti (IP) in females, respectively." (PMID 39264518, 2024). "Dysfunctional inhibitor of nuclear factor-κB (NF-κB) kinase regulatory subunit gamma (IKBKG) is known to trigger incontinentia pigmenti (IP), anhidrotic ectodermal dysplasia with immunodeficiency (EDA-ID), immunodeficiency (ID), and IKBKG deleted exon 5 autoinflammatory syndrome (NDAS)." (PMID 40612668, 2025). "Mutations in IKBKG are associated with the condition incontinentia pigmenti (IP), but if no mutations are detected, an IP diagnosis is excluded." (PMID 39768951, 2024).
Immunodeficiency (62 papers, 2009 to 2026). Failure of the immune system to protect the body adequately from infection, due to the absence or insufficiency of some component process or substance. "While immune function is typically normal in patients with IP, hypomorphic IKBKG variants can lead to immunodeficiency similar to that which occurs in males." (PMID 39860371, 2025). "In recent years, mutant forms of the IKBKG gene have been reported as causative genes of osteopetrosis, lymphedema, hypohidrotic ectodermal dysplasia, and immunodeficiency (OL-EDA-ID)." (PMID 35887342, 2022). "Hypomorphic mutations in inhibitor of NF-κB kinase regulatory subunit gamma (IKBKG) encoding NEMO typically present with immunodeficiency." (PMID 35289316, 2022). "Six patients (P41, P39, P47, P64, P65 and P67) were diagnosed with ectodermal dysplasia with immunodeficiency (EDA‐ID) because of IKBKG deficiency (OMIM: 300248)." (PMID 33777394, 2021). "Individuals with hypomorphic or LoF mutations in IKBKG gene develop severe immunodeficiency, ectodermal dysplasia manifesting with coning teeth, hypodontia and inability to sweat, and colitis." (PMID 34163478, 2021). "Interestingly, some male patients harboring IKBKG variants have been reported to exhibit immunodeficiency characterized by diminished IFN-γ and IL-12 secretion by PBMCs in response to PHA- or CD3-specific antibodies, with no ectodermal disorders as in EDA." (PMID 39860371, 2025). "Hypomorphic variants in IKBKG have been reported in males, leading to the rare form of X-linked hypohidrotic ectodermal dysplasia with immunodeficiency (HED-ID) (OMIM #300291), while in females, they may cause a mild presentation of IP." (PMID 39623400, 2024). "IKBKG/NEMO is essential for activation of the NFkB pathway, which is essential for a plethora of cellular processes involved in immunity, inflammation and proliferation, and mutations result in immune deficiency with ectodermal dysplasia." (PMID 36839544, 2023). "Lastly, unique variants in IKBKG that result in deletion of exon 5 were found to cause an autoinflammatory disease which is also very different from ectodermal dysplasia and immunodeficiency that is typically associated with hypomorphic IKBKG variants that impair NEMO expression and/or function." (PMID 35748970, 2022). "Mutations in IKBKG, the gene encoding NEMO, result in severe colitis, ectodermal dysplasia, and immunodeficiency, including hypogammaglobulinemia." (PMID 40649913, 2025). "NEMO/IKBKG-related ectodermal dysplasia with immunodeficiency (EDA-ID) remains exceptionally rare, with several dozen cases reported." (PMID 41369391, 2025). "NEMO is encoded by the X‐linked IKBKG/NEMO gene and the IKBKG/NEMO mutation leads to immunodeficiency and inflammation." (PMID 38668740, 2024). "Autoinflammatory features and lack of severe infections distinguish NDAS from other disorders due to hypomorphic IKBKG variants impairing NEMO expression and/or function, that are characterized by ectodermal dysplasia and immunodeficiency." (PMID 36870198, 2023). "Of the four patients we selected for LRS, one (25%) received a molecular diagnosis: IKBKG-related immunodeficiency, lending support to this approach." (PMID 36210382, 2022). "Mutations in the IKBKG gene, which encodes NEMO, have been reported in X-linked anhidrotic ectodermal dysplasia with immunodeficiency with osteopetrosis (OL-EDA-ID)." (PMID 35887342, 2022). "First, mutations in the NEMO gene (IKBKG, chromosome X), which generally compromise the ability of NEMO to support activation of NF-κB, lead to a variety of developmental and immunodeficiency diseases in humans." (PMID 31553754, 2019). "Due to the common origin of osteoclasts and macrophages, mutations in IKBKG, CalDAG-GEF1 and kindlin-3 are suspected to be involved in autosomal recessive OP variants with immune deficiency." (PMID 30505439, 2018).